FLT3 (fms related receptor tyrosine kinase 3)
Diseases named in the same sentence as FLT3 in open-access papers (continued):
Sharing a sentence is not in itself a finding about the gene and the disease.
leukemia (continued). "Furthermore, a therapeutic kinase inhibitor directed against all three novel targets, FLT3, BTK, and AURK, may be able to achieve much enhanced anti-leukemia efficacy in the targeted therapy of AML." (PMID 36865133, 2023). "This review provides an overview on the established and evolving potential use of FLT3 inhibitors to prevent or treat AML relapse in post-transplantation context and addresses pending questions regarding its immunogenicity and the mechanisms of leukemia relapse during or after treatment." (PMID 35460465, 2022). "Interestingly, we found that BIO selectively suppressed the proliferation of cells with FLT3-ITD mutations such as MV4-11 and MOLM13 cells, but did not affect the proliferation of leukemia cell lines harboring other types of mutations." (PMID 36481875, 2022). "Although NPM1-mutated AML patients without FLT3-ITD has a good prognosis, those who underwent allogeneic HSCT showed a particularly long-term disease control, probably due to specific graft-versus leukemia effect." (PMID 36008542, 2022). "In regards to pediatric studies, the cut-off value of FLT3/ITD AR was only reported by two large-scale collaboration groups, which were the Children’s Oncology Group (COG) with 630 childhood patients, and Japanese Pediatric Leukemia/Lymphoma Study Group (JPLSG) with a total of 369 samples." (PMID 35760968, 2022). "Indeed, KMT2A-PTD expressing mice do not develop overt leukemia and usually need a second hit such as FLT3-ITD to induce an aggressive myeloproliferative phenotype." (PMID 34068470, 2021). "We measured the expression of genes coding RTKs: FLT3, KIT exclusively in leukemia cell lines, PDGFRa, AXL in NB, NTRK1, FGFR3, INSR, ROR2, and RET in both NB and leukemia cells by qRT-PCR, which were top-scoring RTK-coding genes among leukemia and NB cell lines." (PMID 34944663, 2021). "However, the role of RAC1 in the efficacy of FLT3 inhibitors in the treatment of FLT3-ITD leukemia has not yet been determined." (PMID 34172833, 2021). "We observed reductions in H3K79me2 and STAT5A phosphorylation after 9 days pinometostat treatment, suggesting that DOT1L inhibition may also reduce the viability of non-MLL-rearranged FLT-ITD leukemias through disruption of FLT3-ITD/STAT5A signaling." (PMID 34263728, 2021). "Indeed, by using a surrogate CAR with affinity to murine FLT3, rituximab-mediated depletion of FLT3 CAR T cells after AML eradication enables bone marrow recovery without compromising leukemia remission." (PMID 34041025, 2021). "FLT3-ITD alone does not trigger leukemia, indicating that other drivers are needed for pathogenies." (PMID 33836835, 2021). "However, FLT3/ITD negativity does not imply that residual leukemia cells are absent, and therefore highly sensitive techniques will be required to ensure FLT3/ITD negativity." (PMID 33575214, 2020). "These include mutations in genes known to cooperate with CBF-rearrangements [e.g. NRAS (n = 6), KRAS (n = 4), FLT3 (n = 2), KIT (n = 3), ZBTB7A (n = 2)] as well as in genes, which have not been described to be mutated in CBF leukemia so far (e.g. ZFHX4, NFE2, HERC1)." (PMID 31896782, 2020). "However, in combination with sorafenib (SOME), it induced remission (CR/CRi) in 72% of patients with R/R FLT3-ITD AML, with a deeper molecular response and extended response duration (median overall survival and leukaemia-free survival being 43.6 and 22.4 weeks respectively) among responders." (PMID 32102366, 2020). "Furthermore, we reported a strong linear correlation between expression of the two transcription factors and FLT3 RNA levels in human CN-AML, adding to an increasing body of evidence that points to MYB being a crucial component of leukaemia maintenance and oncogene addiction." (PMID 30877232, 2019).
leukemia (continued). "The other mutations found in AML, such as FLT3-ITD (ITD, internal tandem duplication), FLT3-TKD (TKD, tyrosine kinase domain), NRAS, KRAS, IDH1, IDH2, and MLL-PTD may be lost between diagnosis and relapse as a result of clonal evolution of leukaemia, thus being unstable throughout treatment." (PMID 31661875, 2019). "The Flt3/ITD and Wt1 mutations did not consistently cooperate to recapitulate human AML in our model; thus, a third hit is likely necessary to transform fully to leukemia." (PMID 30450160, 2018). "Taken together, our data highlight the unique dual PIM and FLT3-ITD inhibitory activity of the SEL24-B489 that abrogates signaling circuits involved in proliferation, inhibition of apoptosis, protein translation/metabolism and supporting leukemia initiating cells." (PMID 29682194, 2018). "FLT3L CAR-T cells could specifically kill FLT3+ leukemia cell lines and AML patients’ bone marrow mononuclear cells in vitro (with or without FLT3 mutation) and have more potent cytotoxicity to FLT3-ITD cells." (PMID 29716633, 2018). "In contrast, no cooperativity was observed against wild-type FLT3 leukemia cells." (PMID 30250637, 2018). "The FLT3 receptor is for instance expressed in the most primitive human long-term HSCs, but not in murine LT-HSCs, and it is possible the FLT3 signaling is less important in the GMP-driven MLL-AF9 leukemia models in the mouse compared to more HSC-driven MLL-AF9 leukemia in human CB model systems." (PMID 29240787, 2017). "Importantly, FLT3 is expressed on leukemia blasts regardless of CD34 expression, whereas FLT3 expression is limited to the CD34+ population in normal human BM." (PMID 25295230, 2014). "STAT5 is constitutively phosphorylated and activated in cell lines transfected with FLT3-ITD mutations, as well as leukemia cell lines and primary AML blasts containing endogenous ITD mutations, but STAT5 is not activated in cells with wild-type FLT3, despite stimulation with FL." (PMID 25295230, 2014). "Compared to control IgG-treated mice, mice treated with FLT3 mAb (targeting extracellular FLT3 receptor), or treated with PRL-3 mAb (targeting intracellular PRL-3) showed reduction in the sizes of spleen and liver, two enlarged organs commonly used for indicator of leukaemia burden." (PMID 23929599, 2013). "This suggests that Flt3 is not essential for the self-renewal of the leukemia stem cells." (PMID 23977266, 2013). "Intriguingly, PRL-3 was recently reported as a possible downstream target of FLT3-ITD signalling, with a potential role in drug resistance of leukaemia cells, indicating that PRL-3 expression levels could be an important factor contributing to the outcomes of the AML treatments." (PMID 23929599, 2013). "This could, however, not be validated in an earlier study showing that therapeutic inhibition of Flt3 by PKC412 does not reduce tumor burden of MLL-AF9 leukemia in mice." (PMID 23977266, 2013). "In both these AML cases the ALDHbright compartment contains neither an FLT3-ITD nor an NPM1 mutation (AML-808 and 3G, AML-575 upper panels), indicating HSC, while the ALDHlow compartment has both these leukemia-associated mutations (AML-808 and 3G, AML-575 middle panels), indicating LSC." (PMID 24244383, 2013). "This did not seem to be caused by a lesser proliferation rate of Flt3−/−MLL-ENL blasts as it was not accompanied by reduced leukemia infiltration of organs or longer disease latency, and the proliferation potential of the Flt3−/− and Flt3+/+MLL-ENL blasts was comparable upon ex vivo culture." (PMID 23977266, 2013).
leukemia (continued). "Importantly, we observed synergy between selective Akt inhibitors and FLT3 inhibitors in the absence of stroma as well as its presence, suggesting that this synergy is not specific to leukemia cells growing in a cytoprotective microenvironment." (PMID 23437141, 2013). "In multivariate analysis considering known prognostic factors (age, gender, type of leukemia, cytogenetic risk group, WBC, FLT3/ITD, and NPM1 mutant status), EKLF expression (yes/no) remained an independent favorable prognostic factor for EFS (HR 0.4504, 95%CI 0.2115-0.9589, P = 0.038)." (PMID 22676581, 2012). "None of the patients with identified FLT3 mutations presented recurrent rearrangements in B-ALL or alterations in the IKZF1, PAX5, or ERG genes, suggesting that FLT3 mutation may serve as the driving mechanism for leukemia in these cases." (PMID 39711880, 2024). "Interestingly, whereas CG-806 had low IC50s (i.e., 4 to 10 nM) in most human and murine FLT3-WT leukemia cell lines, its EC50s could not be determined in some human FLT3-WT leukemia cell lines, such as THP-1 and Kasumi-1." (PMID 36865133, 2023). "Similarly, exosomes carry Fas ligand (FAS-L), NPM1, FLT3, matrix metallopeptidase 9 (MMP9), insulin-like growth factor type 1 receptor (IGF1-R), CXCR4, and chaperones to alter the BM microenvironment and to improve the survival of leukemia cells, especially LSCs." (PMID 35865470, 2022). "Finally, we determined the functional relevance of Hmga2 and Flt3 co-expression in G12D/E2-KO HSPCs by measuring the colony-forming activity, which is commonly used to assess hematopoietic or leukemia stem cell activity, with or without FLT3 inhibition and/or HMGA2 depletion." (PMID 34732703, 2021). "However, the anti-proliferative activity was in the low micromolar range in K562 cells, an FLT3-negative leukemia cell line, suggesting that DBPR114 could act via the FLT3 pathway." (PMID 34361230, 2021). "Taken together, our findings suggest that FLT3 inhibitors in advanced stages of development or FDA approved as therapy for mutant FLT3‐positive AML, and representing a wide range of specificity for FLT3, could similarly be considered as treatments for mutant CBL‐positive leukaemia." (PMID 31943762, 2020). "Of clinical relevance, therapeutic targeting of either NPM1 or FLT3-ITD mutations might thus have a transient benefit in restraining disease progression and debulking the leukemia but is unlikely to be curative since will not target the AML-initiating/preleukemic cells." (PMID 31936647, 2020). "However, FLT3-ITD lacking leukemia cell lines were resistant to cabozantinib." (PMID 31694201, 2019). "Although the global leukemia metabolome is not differentiated by FLT3 status, our results establish a precedent that certain metabolic features may differ by disease risk group categories and may have potential to be utilized as biomarkers for risk group classification." (PMID 29615816, 2018). "Combination therapy with FLT3 inhibitors and chemotherapy resulted in improved rates of complete remission (CR) or complete response with incomplete hematological recovery (CRi), although this did not translate into an improvement in leukemia-free-survival or OS." (PMID 27023522, 2016). "However, it was still unclear whether my leukemia would respond to a FLT3 inhibitor—but there were no other reasonable options available to me at the time." (PMID 27148564, 2015). "SETD1B dependency was also observed in the MOLM-13 human MLL-r/FLT3-ITD leukemia cell line but not in the U937 and K562 non-MLL-r leukemia cell lines." (PMID 40341256, 2025). "A strong example of this is the FLT3 enhancer, which is not as large or extensive in either normal cells or other ALL samples compared to MLL-AF4 leukemias." (PMID 37626123, 2023).
leukemia (continued). "Alone, Smc3 haploinsufficiency did not lead to phenotypic changes suggestive of MDS or leukemia, but the addition of Flt3-ITD expression within the mouse model of cohesin insufficiency led to AML with shortened latency compared to Flt3-ITD alone." (PMID 35756660, 2022). "Therefore, our results should not be interpreted to suggest that FLT3 inhibitors would be preferentially active in pediatric AML patients with KMT2A/MLL rearrangements, as many cases without KMT2A/MLL rearrangements whose leukemia cells are FLT3-ITD+ may also benefit from FLT3 inhibitors." (PMID 36627892, 2022). "The combination of talazoparib and quizartinib exerted a strong in vivo inhibitory effect against FLT3-ITDITD;Tet2−/− leukemia, while it was neither effective nor enhanced the effect of the combination in FLT3-ITDITD;Dnmt3a−/− cells." (PMID 35065680, 2022). "In this study, we show that in cell lines established from leukemia patients, endogenous FLT3-ITD but not FLT3-wt clearly accumulates in the perinuclear region." (PMID 34811450, 2021). "Furthermore, it was found that FLT3L CAR-T cells could activate the FLT3/ERK signaling pathway of FLT3+ leukemia cells with wild-type FLT3; meanwhile, it had no inhibitory effects on the colony formation of CD34+ stem cells derived from normal human umbilical cord blood." (PMID 29716633, 2018). "Even though the mice did not develop leukaemia, they observed a transient expansion of CD34+ cord blood cells expressing MLL-AF4 upon FLT3 activation." (PMID 28819864, 2018). "Up to now, the activity of the multi-targeted FLT3 inhibitor, midostaurin, against cells expressing activated SYK has not been explored in the context of leukemia, although SYK has been identified as a target of midostaurin in systemic mastocytosis." (PMID 28881711, 2017). "In leukaemia BM blast cells of mice with MLL-AF9-induced AML, the expression of Crtc1, Flt3 and Mycbp, but not Etv6, was significantly downregulated by co-expressed miR-22 (but not by miR-22 mutant)." (PMID 27116251, 2016). "This provides additional evidence that leukemic blasts are not dependent on Flt3 signaling for tumoral expansion and that in addition to being dispensable for MLL-ENL leukemia initiation, Flt3 appears to be dispensable for leukemia maintenance." (PMID 23977266, 2013). "The reasons for this discrepancy are unclear but we cannot rule out differences in Flt3 requirement between MLL-AF9 and MLL-ENL or MLL-CBP leukemias." (PMID 23977266, 2013). "AML1-ETO, K-Ras and FLT3-internal tandem duplication (ITD) transgenic mice, for example, develop myeloproliferative disorders but not leukemias." (PMID 19960054, 2009). "Taken together, the current research status is not sufficient to answer the question whether FLT3 and CXCR4 act together or independently in leukemia progression." (PMID 37849810, 2023). "Our findings confirmed that CG-806 is a pan-FLT3 inhibitor that may benefit from the simultaneous suppression of FLT3, BTK and AURK activation, leading to a promising anti-leukemia effect against AML regardless of their FLT3 status." (PMID 36865133, 2023). "Indeed, it does not seem judicious to us to treat post-HFD AML mice with Quizartinib, due to the absence of overactivation of FLT3 in post-HFD AML, this treatment should not be able to reduce the leukemia progression." (PMID 32999332, 2020). "The observed correlations between inhibition of Mer or Flt3 and functional anti-leukemia effects mediated by UNC1666 in AML cells suggest that these effects are a result of on-target inhibition of Mer and Flt3, rather than non-specific inhibition of other kinases." (PMID 25762638, 2015). "An FLT3 small-molecule inhibitor demonstrated selective cytotoxicity and reversal of FLT3 activation in SEMK2 and MV4;11 cells, and showed anti-tumor effect in vivo in a leukemia mouse model engrafted with SEMK2, but not with RS4;11 cells." (PMID 25295230, 2014).
leukemia (continued). "We reasoned that under these circumstances, a lack of Flt3 signaling might be more consequential and delay the onset or alter the phenotype of MLL-CBP leukemias." (PMID 23977266, 2013). "Considering the enhancement effect of sorafenib on graft-versus-leukemia (GVL), we conducted a retrospective exploratory study to compare conventional therapeutic strategies combined with or without sorafenib for AML patients with FLT3 wild-type who relapsed after allo-HSCT." (PMID 40830801, 2025). "It is unclear whether FLT3 overexpression alone would confer response to FLT3 inhibitors in KMT2A-r ALL or is merely a consequence of other genomic events and thus not essential for leukemia cell survival." (PMID 36104354, 2022). "In cells into which FLT3-ITD is introduced by a conventional method (e.g., using a viral vector), the ectopic FLT3-ITD gene would be overexpressed, potentially resulting in a phenotype distinct from that of actual patient leukemia cells, which typically may not overexpress the mutant gene." (PMID 34035227, 2021). "However, the anti-proliferative activity was in low micromolar range in leukemia cell lines which are FLT3 negative (U937 and K562), suggesting that BPR1K871 could act through FLT3 target inside the cell." (PMID 27863392, 2016). "In addition, we tested the anti-proliferative ability of BPR1K871 in three other leukemia cell lines - U937 an AML-cell line which is FLT3 negative, RSV-11 cell line which is an ALL cell line with wt-FLT3 and in CML cell line K562 expressing Bcr-Abl fusion protein." (PMID 27863392, 2016).